C6orf141 (chromosome 6 open reading frame 141)
Synonyms: MGC46457
Tractability: No criterion of Open Targets' tractability assessment is met for any kind of drug.
Gene: Protein-coding gene on chromosome 6 (49,550,666 to 49,561,907, forward strand). Ensembl gene ENSG00000197261.
Subcellular location (Human Protein Atlas): Nuclear membrane
Gene Ontology:
Molecular function: protein binding
Genetic constraint (gnomAD): Loss-of-function variants: 0 observed, 0.27 expected, observed/expected ratio (o/e) 0, 90% interval 0 to 1.87. That is too few expected variants to judge how well the gene tolerates losing a copy. Missense variants: 191 observed, 191.98 expected, observed/expected ratio (o/e) 0.99, 90% interval 0.88 to 1.12. Synonymous variants: 91 observed, 80.19 expected, observed/expected ratio (o/e) 1.13, 90% interval 0.96 to 1.35.
Homologues: Orthologues: chimpanzee C6H6orf141 (97% identical), macaque C4H6orf141 (89% identical), rat C9h6orf141 (37% identical), mouse 9130008F23Rik (35% identical), dog C12H6orf141 (34% identical).
Diseases named in the same sentence as C6orf141 in open-access papers:
C6orf141 is named in the same sentence as 18 diseases in open-access papers, as found by Europe PMC text mining. Sharing a sentence is not in itself a finding about the gene and the disease. The quoted sentences say what the papers report.
breast carcinoma (2 papers, 2019 to 2021). "In addition, an analysis of The Cancer Genome Atlas (TCGA) database revealed that low expression levels of C6orf141 were associated with a poor survival rate in patients with breast cancer, endometrial cancer, and head and neck cancer." (PMID 30872783, 2019). "In contrast, high C6orf141 expression was observed to be associated with a more favorable survival curve than that of low C6orf141 expression in patients with head and neck cancer, breast cancer, ovarian cancer, and endometrial cancer." (PMID 30872783, 2019). "According to the Gene Expression Omnibus (GEO), the expression levels of C6orf141 could be silenced in breast cancer cell lines with ZNF217 (Zinc finger protein 217) overexpression." (PMID 30872783, 2019).
oral cancer (2 papers, 2019 to 2023). "In a human genome, a CpG-rich region is located upstream of C6orf141, and our results indicated that C6orf141 plays a tumor-suppressive role in oral cancer." (PMID 30872783, 2019). "Our results implied that C6orf141 expression contributed to oral cancer cell growth by impairing cell cycle progression." (PMID 30872783, 2019). "We examined the expression levels of C6orf141 in eight oral cancer cell lines and the normal epithelial DOK cells through real-time PCR." (PMID 30872783, 2019). "Based on this cutoff value, the patients were separated into two groups, which represented higher and lower C6orf141 expression in oral cancer." (PMID 30872783, 2019). "Our results suggest that C6orf141 plays a novel tumor-suppressive role in oral cancer cell growth and motility." (PMID 30872783, 2019). "C6orf141 has been found as a tumor repressor protein in oral cancer." (PMID 36978083, 2023). "We also examined the expression levels of C6orf141 in oral cancer cells after 5-Aza-dC treatment." (PMID 30872783, 2019). "Our data showed that C6orf141 expression was lower in all oral cancer cells than in DOK cells." (PMID 30872783, 2019). "Consistent with its clinical effects, ectopic C6orf141 expression could suppress oral cancer cell growth and invasion, implying that C6orf141 plays a tumor-suppressive role in OSCC progression." (PMID 30872783, 2019). "Because C6orf141 expression was downregulated in oral cancer, gain of function might be a more effective approach to studying the biological function of C6orf141." (PMID 30872783, 2019). "C6orf141 (Chromosome 6 open reading frame 141) is a novel gene, and its role in oral cancer progression remains unclear." (PMID 30872783, 2019). "Ectopic C6orf141 expression could significantly suppress oral cancer cell proliferation." (PMID 30872783, 2019). "In summary, our results indicate that C6orf141 may act a tumor suppressor in oral cancer." (PMID 30872783, 2019). "Additionally, ectopic C6orf141 expression could significantly suppress oral cancer cell proliferation, colony formation, and migratory and invasive abilities." (PMID 30872783, 2019). "Furthermore, C6orf141 knockdown could significantly accelerate oral cancer cell proliferation, migration, and invasion ability." (PMID 30872783, 2019). "Taken together, the results suggested that DNA methylation is not the major factor resulting in low C6orf141 expression in oral cancer progression." (PMID 30872783, 2019). "Results revealed that the expression levels of C6orf141 could not be increased in most oral cancer cell lines, except for SAS cells, after 5-Aza-dC treatment." (PMID 30872783, 2019).
breast tumor (1 paper, 2024). "The capability of STGIC is validated indirectly by expression of marker genes of invasive breast tumor in the predicted spatial domains, which are C6orf141, PDE5A, LINC00645, BMERB1, ABCC11, ABCC12." (PMID 38416785, 2024).
colon cancer (1 paper, 2019). "The expression levels of C6orf141 were determined to be significantly reduced in thyroid cancer and testicular cancer, whereas those of C6orf141 were determined to be increased in colon cancer and lung cancer (data not shown)." (PMID 30872783, 2019).
gastric cancer (1 paper, 2019). A primary or metastatic malignant neoplasm involving the stomach. "Based on TCGA database, high C6orf141 expression was noted to be significantly correlated with poor survival rates in patients with liver cancer, pancreatic cancer, kidney cancer, and gastric cancer." (PMID 30872783, 2019).
oral squamous cell carcinoma (1 paper, 2019). "C6orf141 expression in oral squamous cell carcinoma (OSCC) and adjacent normal tissues from 428 patients was examined through immunohistochemistry (IHC)." (PMID 30872783, 2019).
cancer (1 paper, 2019). A tumor composed of atypical neoplastic, often pleomorphic cells that invade other tissues. "Low C6orf141 expression was significantly associated with a poor American Joint Committee on Cancer pathological stage (P < 0.001), T classification (P = 0.002), and pN stage (P = 0.032)." (PMID 30872783, 2019). "An analysis of the relevant databases indicated RNA levels of C6orf141 to be inconsistent in different human cancers." (PMID 30872783, 2019). "Our study demonstrated that C6orf141, a novel cancer-related gene, has a tumor-suppressive role in OSCC cell growth and invasion." (PMID 30872783, 2019). "Perhaps, miR-335 suppressed cancer cell motility through inhibiting C6orf141 expression in OSCC." (PMID 30872783, 2019). "With these combined results, using mRNA to evaluate the clinical effects of C6orf141 in human cancer might result in some uncertainties." (PMID 30872783, 2019).
tumor (1 paper, 2019). "Little information for C6orf141 on the roles in tumor-related function has been identified." (PMID 30872783, 2019). "Additionally, C6orf141 expression in tumor tissues was significantly different among the BMSCC and TSCC." (PMID 30872783, 2019). "Xenograft tumor growth indicated that C6orf141 expression could significantly reduce tumor volume and size in vivo." (PMID 30872783, 2019). "To assess the effects of C6orf141 expression on tumor growth in vivo, we generated SAS cells with stable C6orf141 expression." (PMID 30872783, 2019). "Our results reveal a significantly lower C6orf141 expression level along with advanced pathological stage (I vs II + III + IV, P < 0.001) and large tumor size (T1 vs T2 + 3 + 4, P < 0.005) in BMSCC, but not in TSCC." (PMID 30872783, 2019).
C6orf141 also shares sentences with these, for which no sentence is quoted: endometrial cancer (1 paper); head and neck cancer (1); kidney cancer (1); liver cancer (1); lung carcinoma (1); ovarian carcinoma (1); pancreatic cancer (1); testicular cancer (1); thyroid cancer (1); triple-negative breast carcinoma (1).